S100A8 (S100 calcium binding protein A8)
Diseases named in the same sentence as S100A8 in open-access papers (continued):
Sharing a sentence is not in itself a finding about the gene and the disease.
infection (continued). "Given the decreased worm burden in S100A8/A9-/- mice that was also present after subcutaneous infection, which bypasses the epidermis and dermis, we next assessed S100A8/A9-dependent immunological changes within the skin 3h after intradermal injection of mice with 10 L3 larvae." (PMID 32107497, 2020). "Infection-induced inflammation is one of the main resources for S100A8/A9 secretion." (PMID 29942307, 2018). "S100A8/A9 may exert its host defense functions locally upon neutrophil death mediated release at sites of tissue infection, thereby controlling growth of P. aeruginosa." (PMID 28672877, 2017). "In this cohort, the S100A8/A9 complex increased significantly over time (p = 0.001), but its levels increment over time (D0 to D5) was significantly smaller in patients developing infection (7.6 vs 40.1 mcg/mL, p = 0.011)." (PMID 29178941, 2017). "Thus, we assessed the impact of recombinant S100A8/A9 on the course of infection in BALB/c mice as well as the direct inhibitory effect on S100A8/A9 in vitro." (PMID 28672877, 2017). "Two selected ECM-MP proteins, carbonic anhydrase 1 (CA-I) and S100A8, were further verified on a larger number of samples and their abundance was proven to be increased within plasma MP specifically released during the infection." (PMID 27917875, 2016). "We next investigated the capacity of murine whole blood cells to release S100A8/A9 in the systemic compartment following infection and found that whole blood from WT mice stimulated for 4 hours with S. Typhimurium released S100A8/A9 complexes in a dose dependent manner (P = 0.016)." (PMID 25860480, 2015). "Indeed, lowering the stringency of the microarray analysis allowed the identification of over 70 genes, including several genes known to be associated with the mammary gland response to infection, e.g. SOD2, IL1B, LTF, S100A8 and S100A12." (PMID 23324411, 2013). "Similarly, other genes associated with the mammary gland response to infection are expressed at higher levels in SA24T0, e.g. S100A8, S100A12, CXCL10, interleukin (IL) 1B and lactotransferrin (LTF)." (PMID 23324411, 2013). "In previous studies, we found that infection with HV-68 could induce the production of S100A8 and S100A9, and could also expand a population of CD11b+Gr-1+MDSCs in vivo." (PMID 22946998, 2012). "Previous studies demonstrated that HV-68 infection alone could induce S100A8/S100A9 in vivo during acute infection and viral latency, which was consistent with increased MDSCs in these infected mice." (PMID 22946998, 2012). "Here we questioned whether HV-68 infection of cultured, myeloid-derived macrophages and dendritic cells could result in the increased expression of S100A8 and S100A9." (PMID 22946998, 2012). "As S100A8/A9 might play a role during a less severe infection, we infected WT and S100A9 KO mice with 4.5×108 CFU/mouse." (PMID 20976233, 2010). "This shows the contribution of S100A8/A9 in systemic infection, however its contribution in local infection is unknown." (PMID 20976233, 2010). "The expression of S100A8/A9 has been investigated in several infection models." (PMID 20976233, 2010). "In fact, the reduced expression of S100A8, which is one of the antimicrobial proteins against C. rodentium and is regulated by IL-22, was also detected in VillinCre-p38ΔIEC epithelial cells after infection." (PMID 20532209, 2010). "In conclusion, S100A8/A9 deficiency did not influence the host response after infection with two doses of uropathogenic E. Coli, suggesting that endogenous S100A8/A9 does not play a major role in the pathogenesis of E. Coli-induced UTI." (PMID 20976233, 2010). "The platelet aggregation protein thrombospondin 1, which was up-regulated 2.2-fold in our microarray data, indicates that the thrombogenic response induced by S100A8/A9 in endothelium may have been activated following HPS infection." (PMID 19196461, 2009).
infection (continued). "In addition to neutrophil recruitment, S100A8/A9 acts to sequester metals/nutrients (calcium, iron, zinc, manganese) as part of a process termed nutritional immunity in which metal-chelating host defense mechanisms are used to prevent infection." (PMID 40386438, 2025). "Indeed, blood levels of S100a8/a9 increased drastically on day 2 post-infection." (PMID 37396347, 2023). "Hence, S100A8/A9 inhibits the growth of pathogens at infectious sites during the initial phase of infection, allowing time for the recruitment of phagocytes, and then, S100A9 enhances the phagocytic activity of infiltrating leukocytes, accelerating the clearance of pathogens." (PMID 29942307, 2018). "Importantly, treatment by S100A8/A9 provides local infection control." (PMID 28672877, 2017). "As infection progressed, we detected a robust upregulation of genes encoding cytokines and chemokines (CCL2, CCL3, IL1B, CXCR1, IL1RN) as well as granulocyte associated transcripts (TLRs 1-4, SPI1, S100A8, S100A9, CD177), which correlated with the higher numbers of granulocytes 5 DPI." (PMID 28852031, 2017). "The complement component C8a and S100 proteins, S100a8 and S100a9, were highly differentially abundant in both infected strains, signifying a potential innate immune response and the importance of the complement pathway in defence against macroparasite infection." (PMID 27490109, 2016). "The ability of HV-68 infection to induce S100A8 and S100A9 production and to expand a population of CD11b+Gr-1+ cells suggested that increased numbers, or activity, of viral-expanded myeloid derived suppressor cells (MDSCs) might contribute to HV-68-associated metastatic breast cancer in this model." (PMID 22946998, 2012). "In SLE patients, the expression of S100A8 and S100A9 on the surface of dendritic cells is notably increased, especially during periods of infection." (PMID 39877611, 2025). "The expression level of several proinflammatory genes including TYROBP, S100A8, S100A11, LBP and CD88 were increased significantly after infection." (PMID 39398025, 2024). "The results of serum sample testing showed that these mAbs specifically identified the proteins S100A8, S100A9 and S100A12 in the serum and were able to evaluate changes in the protein content of S100A8, S100A9, and S100A12 during infection." (PMID 38256103, 2024). "S100A8/A9 molecules (also known as MRP8/P14), mainly released by monocytes, neutrophils and macrophages during infection, can modulate inflammation by inducing pro‐inflammatory cytokines." (PMID 39135683, 2024). "Apart from playing a vital role in human health and diseases, S100A8, S100A9, and S100A12 proteins are closely related to the infection (including bacteria, viruses, and parasites) process in pigs." (PMID 38256103, 2024). "Although, we observed an overall decrease in the alveolar macrophage population in the BALF of both WT and S100A8/A9, there was a significant increase in number of infiltrating inflammatory macrophages (F4/80+ CCR2+ cells) in S100a9 KO mice upon infection." (PMID 37624851, 2023). "Importantly, the S100a8/a9 protein levels steadily increased over time in the S. aureus Newman-infected knee joints of mice with a median value ranging from 3.415 on day 1 to 18.05 on day 3 and 26.48 on day 9 after infection, as compared to 0.6361 in healthy controls." (PMID 37396347, 2023). "Differential gene expression analysis revealed a common epithelial host response to mycobacteria, including upregulation of BIRC3, S100A8 and DEFB4, and downregulation of BPIFB1 at 48 h post infection." (PMID 37822359, 2023). "When CAP occurs due to infections, phagocytes are stimulated by PAMP molecules to secrete S100A8/A9 and migrate toward the center of inflammation." (PMID 37180431, 2023).
infection (continued). "Infection with Salmonella Typhimurium SL1344 led to disordered colonic microbiotas, colonic inflammation through the S100A8/S100A9–NF-κB pathway and potential apoptosis, and translocation of pathogens to parenteral visceral organs in mice." (PMID 35658572, 2022). "During inflammation or tissue damage, S100A8/A9 is actively secreted by neutrophils and monocytes, and represents the most abundant DAMP/alarmin activating inflammatory processes in infection, cancer, autoimmunity, and cardiovascular diseases." (PMID 35543413, 2022). "Calprotectin, also known as S100A8/S100A9 heterocomplex, is a protein involved in the innate immune response to infection." (PMID 34054868, 2021). "Most notably, survivors with mild disease had an ∼30-log2-fold reduction in the expression of S100A8 and S100A9 early after infection, whereas survivors with severe disease exhibited an ∼2-log2-fold reduction." (PMID 34372693, 2021). "After 1 day of infection, the oral tissues of the gefitinib-treated mice contained significantly less CXCL1/KC, CCL20, IL-1α, IL-1β, IL-17A, and the host defense peptide S100A8 than control mice." (PMID 33471869, 2021). "Mtb-AG infection significantly upregulated the expression of inflammatory molecules S100A8, S100A9, CRP, IL23, activated NK cell marker (KLRG), and Th-2 type marker, IL10 at 1 week post infection." (PMID 34732811, 2021). "The S100A8/S100A9 heterodimer, also known as calprotectin, is abundantly expressed by neutrophils and markedly increased during infection, tissue damage, neutrophil extracellular trap formation (NETosis) and cellular necrosis." (PMID 32107497, 2020). "The elevated level of S100A8/S100A9 amplifies inflammation and enhances the inflammatory response in infection, making it a potential therapeutic target in anti-inflammatory strategies." (PMID 32076015, 2020). "There are other types of cells that can release S100A8 and S100A9 upon infection; for example, during hidradenitis suppurativa infection, keratinocytes are one of the most important sources of S100 proteins." (PMID 29942307, 2018). "To functionally characterize the role of S100A8/A9, we challenged wildtype (WT) and S100A9-/- mice with S. Typhimurium and determined bacterial loads and inflammation 2- and 5- days post infection." (PMID 25860480, 2015). "Mice eventually controlled the infection, as indicated by a reduction in fungal burden, PMN number, S100a8 and S100a9 expression, calprotectin level and amelioration of inflammatory pathology at 21 and 42 dpi." (PMID 23853597, 2013). "The presence of such high levels of S100A8 and S100A9 following infection, and the importance of these proteins for expanding MDSC, suggests one likely mechanism to account for the accumulation of HV-68 induced CD11b + Gr1+ cells in the spleen." (PMID 22507226, 2012). "Late infection featured further Th1 reduction, neutrophil accumulation, and NETs activation (H3cit, NE-DNA, MPO), along with reduced CXCL9 but elevated IL-6, IL-21, IL-27, CXCL10, and S100A8 in blood." (PMID 42112327, 2026). "Notably, myeloid cells in AG ferrets showed significantly elevated expression of inflammatory cytokines, including IL-1β, IL-10, IL-18, NFκB1, and S100A8, as well as upregulated IFNGR2 expression throughout infection, especially 4dpi." (PMID 40794649, 2025). "Plasma S100A8 and S100A9 had high specificity and sensitivity in predicting infection." (PMID 39575241, 2024). "Compared to susceptible mice, CD-1 mice exhibited less fungal burden over 6 days of the infection, but similar neutrophil recruitment, IL-1β and alarmin S100A8 levels, with a declining but not significant trend over the infection." (PMID 39234208, 2024). "Exogenous IFNλ has been shown to inhibit neutrophil recruitment and uptake of bacteria during infection, and neutrophils regulate type 17 immune responses, although the S100A8 Cre is not 100% specific to neutrophils." (PMID 39178311, 2024).
infection (continued). "The expression of S100A8/A9 in the infection-induced inflammatory response is limited by a negative feedback regulation mechanism." (PMID 39061526, 2024). "In this context, previous reports suggested that lack of S100A8/A9 impaired CD11b dependent neutrophil recruitment to the site of infection." (PMID 37467233, 2023). "S100A8 and S100A12 are among the most highly expressed genes on average throughout infection." (PMID 35019713, 2022). "After infection of Cas9-expressing ER-Hoxb8 precursor cells with CRISPR library lentiviral particles, the cells were differentiated for 3 days in the presence of GM-CSF to induce S100A8 and S100A9 expression." (PMID 35543413, 2022). "S100A8- and S100A9-expressing cells (see circles) were already present 4 dpi before CD3+ T lymphocytes (see circle) infiltrate the cardiac tissue, suggesting that not T cells but rather MDSC are the major S100A8 and S100A9 producers early in infection." (PMID 34065891, 2021). "Irrespective of disease severity, the levels of S100A8/A9 were elevated in all the individuals with asymptomatic (p<0.0001) and symptomatic (p<0.0001) infections, when compared to the healthy controls." (PMID 34746027, 2021). "Serum and fecal S100A8 did increase during the course of infection in both AKR and BALB/c mice, but no statistical differences were observed, and there was high variability between mice." (PMID 31840738, 2020). "S100A8/9 is known to be expressed and secreted during infection-induced inflammation and is restricted by a negative feedback regulatory mechanism." (PMID 33082228, 2020). "The expression and secretion of S100A8/9 during infection-induced inflammation are restricted by a negative feedback regulatory mechanism." (PMID 29942307, 2018). "The patients where the S100A8/9 circulating complex did not increase significantly between D0 and D5 were more prone to infection." (PMID 29178941, 2017). "Proteins S100a8 and S100a9 were among the most abundantly expressed under infection in both mouse strains, and completely absent in the control samples." (PMID 27490109, 2016). "Western blots indicated that protein production for IL-1β, S100A8, and S100A9 is significantly increased upon infection (lanes denoted by “I”), which confirms the RNA-seq data for the genes encoding these proteins and further validates the RNA-seq data as a whole." (PMID 25901897, 2015). "In plasma, low S100A8/A9 levels in uninfected mice (median 126 ng/ml) increased approximately 8-fold 5 days post-infection with S. Typhimurium irrespective of the inoculum (median 969 ng/ml with 105 CFU; 980 ng/ml with 106 CFU, P = 0.024)." (PMID 25860480, 2015). "When mice were infected with Salmonella, the levels of S100A8/A9 were also elevated but mice lacking this protein did not have an altered host response to infection." (PMID 25860480, 2015). "Compared to uninfected controls at day 7, infection of non-Tg mice with C. albicans significantly (p < 0.05) enhanced tongue tissue expression of S100a8, Ccl20, Il17, Il22 and, to a lesser degree, of the Dfb3 gene." (PMID 25344377, 2014). "In C57BL/6 mice, fetal infection did not affect the expression of IL-1α or S100A8 in U. parvum infected placentas." (PMID 22952869, 2012). "The late emergence of State 6, marked by apoptotic signaling genes (THBS1, IL1R2, S100A8), suggested that ASFV may eventually trigger cell death in heavily infected macrophages, potentially contributing to the cytopathic effects observed in advanced infection." (PMID 40723441, 2025). "The levels of plasma S100A8/A9 were not dependent on the site of infection." (PMID 37773186, 2023).
infection (continued). "To investigate whether A/J neutrophils displayed enhanced release of these mediators in the airways during infection, we assayed the presence of neutrophil elastase, MPO, and S100A8 in BAL fluid from mice at day 5 PI when lung neutrophil numbers had equilibrated between the strains." (PMID 36685578, 2022). "However, S100A8/S100A9 response was found not to be critical for infection control in a murine model of UTI." (PMID 29145515, 2017). "However, since the biological activities of S100A8, S100A9, and S100A12 proteins are affected by redox conditions, pH, metabolite, and nutrient distribution at the site of infection, it is unclear whether the changes in protein expression are consistent with their biological activities yet." (PMID 38256103, 2024). "Importantly, downregulation of S100a8/a9 mRNA expression at the early course of infection was noticed in mice infected with the S. aureus Sortase A/B mutant strain totally lacking arthritogenic capacity compared with the mice infected with parental S. aureus arthritogenic strain." (PMID 37396347, 2023). "In addition, the type 1 IFN related genes (OAS1G, OAS2, OASL1, OASL2, S100A6, S100A8, S100A9, S100A11) that are necessary for activation of the inflammasome in Francisella novida-infected macrophages, were highly induced over the course of infection and peaked at 24 hpi." (PMID 21110886, 2010). "Interestingly, S100 family proteins are involved in the regulation of a number of cellular processes, and two members of this gene family, S100A8 and S100 A9, were significantly up-regulated with a large fold change at 4 days post infection relative to non-infected mouse." (PMID 21172007, 2010). "Next, 109,584 cells from 4 non-human primates at 10 weeks after infection with MTB6 were used to observe the expression of two genes, S100A12 and S100A8." (PMID 40415930, 2025). "In a previous work we demonstrated that children who present febrile symptoms without apparent infection have elevated concentrations of HMGB1 and S100A8 proteins (unpublished data)." (PMID 40868835, 2025). "To address the current lack of reliable and timely detection tools for porcine S100A8, S100A9, and S100A12 proteins during the infection process, we generated mAbs specific to these three proteins in this study using hybridoma technology." (PMID 38256103, 2024). "Following infection with a non-lethal dose of IAV (50 pfu), S100a8-Cre/Acvr1bfl/fl animals exhibited a worse phenotype compared to controls." (PMID 38476229, 2024). "Immunohistological stainings provide evidence that rather MDSC and not T cells are the main S100A8 and S100A9 producers early in infection; the absence of MDSC resulted in a reduced cardiac expression of S100A8+ immune cells." (PMID 34065891, 2021). "Treatment with FliC did not modulate the levels of S100A8 and S100A9 in both groups of mice at both 24 and 48h after infection." (PMID 33784296, 2021). "Thus, one could speculate that the lack of S100A8/A9 is an expression of a chronic infection: The host defense is incapable of resolving the local infection, as PMNs are efficiently recruited from the blood to the site of infection but are counteracted by the close proximity to the biofilms." (PMID 32664205, 2020). "No such downregulation of S100A8 and S100A9 was observed by infection with UV-inactivated virus when compared with mock infected cells." (PMID 30677738, 2019). "During an infection with Gram-negative bacteria, as a ligand for TLR4, S100A8 is strongly induced in endotoxic shock." (PMID 29942307, 2018). "After infection with S. Typhimurium a marked increase of S100A8 and S100A9 expression was observed in liver and spleen but not at the local site of infection (colon)." (PMID 25860480, 2015). "In vitro studies demonstrated that direct exposure of myeloid cells to HV-68 did not induce increased expression of S100A8 or S100A9 mRNAs or secreted protein regardless of the multiplicity of infection or time following infection." (PMID 22946998, 2012).